CD47 (CD47 molecule)
Diseases named in the same sentence as CD47 in open-access papers (continued):
Sharing a sentence is not in itself a finding about the gene and the disease.
cancer (continued). "Finally, an additional interesting checkpoint is CD47, a “do not eat me” antiphagocytic signal that forms a signaling complex with signal-regulatory protein α (SIRPα), enabling the escape of cancer cells from macrophage-mediated phagocytosis and other phagocytes." (PMID 33562694, 2021). "However, due to the elevated expression of CD47 in the 3D stem-like spheroids and xenografts, we hypothesize that CD47 is a more robust CSC marker and better marker of prognosis to be a clinically validated target for cancer immunotherapy." (PMID 34205080, 2021). "TTI-621, a recombinant protein that blocks the CD47-SIRPα signaling in humans, is currently being studied in clinical trials including multiple solid tumors based on previous xenograft studies where it improved macrophage phagocytosis of cancer but not normal cells." (PMID 32326073, 2020). "Therefore, this may represent a widely applicable treatment approach for various cancers, including those with limited or no CD47 expression." (PMID 33603751, 2020). "Interestingly, CD47 was recently shown to promote a Warburg phenotype by protecting the ubiquitin mediated degradation of ENO1, a glycolytic enzyme, providing another role of CD47 in cancer metabolic rewiring, in addition to its established role in immune evasion." (PMID 33256070, 2020). "Considering that SF protein could mediate ADCC effect on CD47‐positive cancer cells in vitro, the enhanced antitumor capacity of oncolytic adenovirus SG635‐SF on CD47‐positive xenografts might be due to both phagocytosis enhancement and ADCC effect via CD47 blockade by the SF protein." (PMID 31899582, 2020). "Thus, for all of the macrophage subtypes found in the TME of DLBCL, SLAMF7 expression on cancer cells is not required for anticancer activity upon CD47 targeting, with M2 macrophages appearing to respond more effectively to CD47-targeting than M1 macrophages while having lower SLAMF7 expression." (PMID 30710089, 2019). "However, CD47 signaling in nontransformed and some malignant cells regulates self-renewal, suggesting that CD47 antibodies may therapeutically target cancer stem cells (CSCs)." (PMID 26840086, 2016). "Thus, the enhanced phagocytosis of human cancer cells by human macrophages could be mediated by the blockade of CD47-SIRPα signaling, but not in an Fc-mediated fashion." (PMID 26077800, 2015). "Conversely, the expression levels of CD47 and CD86 proteins on cancer cells were not affected by lamin knockdown." (PMID 40708945, 2025). "Mice that are re-challenged with chromosomally stable CD47 KO tumors (and without exogenous anti-Tyrp1 opsonization) shows increased median survival and increased immune infiltrate, further supporting the hypothesis of newly generated anti-cancer acquired immunity." (PMID 37066426, 2024). "Mice that are re-challenged with chromosomally stable CD47 KO tumors (and without exogenous anti-Tyrp1 opsonization) show increased median survival and increased immune infiltrate, further supporting the hypothesis of newly generated anti-cancer acquired immunity." (PMID 38805560, 2024). "Reversely, expression of the pro-phagocytic receptor SLAMF7 was reported to be crucial for execution of macrophage-mediated phagocytosis of cancer cells, although cancer cell-expression of SLAMF7 is not required for CD47 antibody treatment." (PMID 38116002, 2023). "Nicotine exposure additionally helps maintain immune tolerance and restrain cancer autoimmunity by increasing the mRNA expression of negative immunoregulatory proteins such as PDL1 and CD47." (PMID 37566079, 2023). "Neutrophils were found to destruct antibody-opsonized cancer cells not by ADCC but rather by trogocytosis, and blocking the CD47-SIRPα interaction further potentiates this activity." (PMID 34729396, 2021). "In conclusion, cancer cell expression of SLAMF7 is not required for phagocytosis and, in contrast to CD47 expression, should not be used as selection criterion for CD47-targeted therapy." (PMID 30710089, 2019).
cancer (continued). "Moreover, anti-CD47 antibody could not induce phagocytosis of non-cancer or normal cells in vitro." (PMID 28484448, 2017). "Humanized CD47-CAR-T cells effectively killed CD47-positive cancer cells and had no killing activity against Hela-CD19 cancer cells with very low expression of CD47, while positive control CD19-CAR-T cells effectively killed Hela-CD19 cells." (PMID 29065481, 2017). "The humanized CD47-CAR-T cells effectively killed cancer cell lines with a high expression of CD47 and did not kill and did not produce cytokines in CD47-negative cancer cells." (PMID 29065481, 2017). "Furthermore, targeting of "do-not-eat-me" signals with anti-CD47 and anti-CD24 monoclonal antibodies demonstrate differential effects on macrophage activity and cancer cell viability, again depending on the individual malignant cell line." (PMID 41881987, 2026). "Finally, TNFSF10—TNFRSF10B (TRIAL—TRIAL-R), SIRPA—CD47 (“don't eat me”), C5AR1—RPS19, and GAS6—AXL act as negative regulators of the innate immune system by inhibiting cytokine responses, phagocytosis of cancer cells, and promoting the immunosuppressive TME." (PMID 37823774, 2023). "The mechanism by which THGP promoted cancer cell phagocytosis might involve the suppression of SIRP-α and CD47 (two “do not eat me” signals) expression." (PMID 36768216, 2023). "Thus, CD24 antibody treatment potentiated phagocytosis with greater effect in vitro than CD47 mAb treatment in MCL and carcinoma, but not in DLBCL." (PMID 35625912, 2022). "Thus, the effect of a clinically relevant CD47 blocking IgG4 antibody is mediated by blocking of the SIRPα/CD47 interaction and does not require expression of SLAMF7 on cancer cells." (PMID 30710089, 2019). "Expression of SLAMF7 on cancer cells also did not impact on the in vitro phagocytic activity of macrophages upon treatment with the CD20 antibody rituximab alone, or in combination with CD47 antibody inhibrix." (PMID 30710089, 2019). "The fact that target cells without CD47 expression were still targets for CTL killing, albeit to a lesser extent than targets with CD47 expression, is important when considering using CD47 blockade to treat cancer." (PMID 30770827, 2019). "CD47, which was upregulated in all DEN/TAA/HFD treated mice compared to DEN/TAA treated mice and controls, is a negative prognostic factor for a variety of cancers, and acts as a “don’t eat me” signal for many cancers." (PMID 29980757, 2018). "However, as a subgroup of CSC, L3 does not express genes related to cancer dormancy (FN1, CD47, and THBS1); therefore, L3 is a smaller, independent cluster that expresses high levels of stem cell markers while lacking the expression of cancer dormancy marker genes." (PMID 37858183, 2023). "Interestingly,the high efficiency of CD47 knockdown was obtained by using the LNPsand BNP carriers; however, an increase in CRT levels on cancer cellswas not required for phagocytosis to happen in co-culture with humanmacrophages, indicating other pathways’ involvement in thephagocytosis process." (PMID 36632842, 2023). "We hypothesized that early-stage CIN in cancer cells can stimulate anti-cancer activity of macrophages sufficient to dominate proliferation of high CIN tumors, but probably only when maximizing pro-phagocytic conditions, such as with blockade of SIRPα (rather than ubiquitous CD47)." (PMID 38805560, 2024).
hematologic malignancies (71 papers, 2017 to 2025). "We review the latest clinical research advances and discuss the opportunities and challenges associated with CD47-based immunotherapy for hematological malignancies." (PMID 38464520, 2024). "CD47 upregulation has been reported in hematologic malignancies such as NHL, MM, and Leukemias and is associated with poorer prognosis." (PMID 37920162, 2023). "Notably, high CD47 expression has been associated with poor prognosis in various solid and hematological malignancies." (PMID 41233805, 2025). "Currently, over 10 CD47-related therapeutic agents are undergoing evaluation in more than 40 clinical trials worldwide, targeting various hematological malignancies as well as solid tumors." (PMID 41383500, 2025). "Anti-CD47 antibodies have been shown to achieve objective (total or partial) remission in 50% of patients by showing considerable anticancer activity in hematological malignancies." (PMID 40589735, 2025). "To date, clinical trials assessing mAbs targeting CD47 have shown promising results in hematological malignancies, whereas studies on solid tumors are still limited." (PMID 41233805, 2025). "SIRP-α is highly expressed on the surface of myeloid cells, and its interaction with CD47 provides a “don’t eat me” signal to macrophages, therefore CD47 antibodies are used in the treatment of hematological malignancies." (PMID 40308591, 2025). "Numerous studies have shown promising preclinical results for anti-CD47 therapies in treating hematologic malignancies." (PMID 40013150, 2025). "CD47 is overexpressed on various solid and hematologic malignancies in order to escape the immune system." (PMID 40369208, 2025). "Currently, 11 CD47 antagonists are undergoing clinical trials for the treatment of hematological malignancies, with published clinical research data available for some of these CD47 antagonists." (PMID 39040441, 2024). "In this article, we review the new developments in CD47-based immunotherapy for hematological malignancies." (PMID 38464520, 2024). "CD47 is overexpressed in hematological malignancies and solid tumors alike to evade phagocytosis by macrophages." (PMID 38414061, 2024). "It is noteworthy to acknowledge that CD47 blockade has demonstrated remarkable success in the treatment of hematological malignancies." (PMID 38493445, 2024). "Although CD47 blockade is powerful in hematologic malignancies, its efficacy in solid tumors has been much less rewarding." (PMID 39335665, 2024). "To date, the majority of work to target phagocytosis has focused on disruption of CD47-SIRPα through the blockade of CD47, with numerous phase 1–2 clinical trials underway in hematological malignancies and solid tumors." (PMID 38577107, 2024). "Clinical trials have shown that targeting CD47 can be an effective therapeutic strategy in treating hematologic malignancies." (PMID 39275127, 2024). "The expression of the cell surface glycoprotein CD47 is elevated in many solid tumors and hematologic malignancies." (PMID 39201643, 2024). "Despite the therapeutic success of CD47 blocking antibodies in hematological malignancies, their efficacy is limited in solid tumors." (PMID 38414061, 2024). "The CD47-SIRPα axis is a novel antitumor target that has shown promising results in clinical studies for the treatment of hematological malignancies." (PMID 38464520, 2024). "To summarize, we reported a novel strategy for treating hematologic malignancies that are CD38-positive by simultaneously targeting CD47 and CD38 via a first-in-class bispecific antibody." (PMID 38983860, 2024). "Macrophage immune checkpoint inhibitors, such as anti-CD47 antibodies, show promise in clinical trials for solid and hematologic malignancies." (PMID 38483480, 2024). "Despite the encouraging clinical efficacy observed in hematologic malignancies through CD47-SIRPα blockade, there are safety concerns related to the binding of anti-CD47 antibodies to CD47 on the membrane of peripheral blood cells." (PMID 38429732, 2024).
hematologic malignancies (continued). "Magrolimab, a humanized monoclonal antibody against CD47, is currently being evaluated in several clinical trials for hematological malignancies." (PMID 38464520, 2024). "The CD47/SIRPα axis has been identified as a potential future immunotherapeutic target for hematological malignancies." (PMID 36726125, 2023). "Overexpression of CD47 has been strongly correlated with poor therapeutic outcomes in both solid and hematological malignancies." (PMID 37444515, 2023). "Nevertheless, the CD47‐SIRPα interaction/phagocytic mechanism remains a promising target for treatment of patients with solid tumors and hematologic malignancies and should continue to be explored." (PMID 37206279, 2023). "The “don’t eat me” signal CD47 was proved to be an essential mechanism of immune evasion in hematological malignancies." (PMID 36543880, 2023). "CD47-blocking antibodies such as Hu5F9-G4 and CC-90002 are currently being evaluated in clinical trials for various solid tumors and hematological malignancies." (PMID 38188674, 2023). "CD47 is highly expresses on several hematological malignancies and solid tumors to inhibit innate immunity of myeloid cells 31-33." (PMID 36593962, 2023). "Further studies should evaluate the influences of CD47 inhibitors in combination with CAR-T cell therapy in hematological malignancies." (PMID 35978372, 2022). "More studies are also required to evaluate the effect of CD47/SIRPα-targeted ADCs on hematological malignancies." (PMID 35978372, 2022). "CD47 expression has been found to be considerably elevated in numerous hematological malignancies, as well as solid cancers." (PMID 35978372, 2022). "Increased expression of CD47 has been documented in hematological malignancies and also in various human solid tumors." (PMID 35406573, 2022). "Based on this research, CD47/SIRPα-targeted BsAbs are potential treatment options for hematological malignancies." (PMID 35978372, 2022). "In hematological malignancies, those that block the CD47/SIRPα axis and PD-1/PD-L1 axis have demonstrated promising clinical responses." (PMID 35978372, 2022). "Significant progress has been made in research in Bispecific T cell engagers (BiTE) and anti-CD47/SIRPα antibodies in the treatment of hematological malignancies." (PMID 35978372, 2022). "Accumulating evidence shows that various solid and hematologic malignancies overexpress the CD47 protein on the surface as a protective “self-marker”." (PMID 34584838, 2021). "This class of therapeutics constitute the majority of the available in-human data testing CD47/SIRPα inhibition in solid tumors and hematologic malignancies, although data remains limited." (PMID 34944850, 2021). "Magrolimab, previously known as Hu5F9-G4, is a humanized IgG4 anti-CD47 mAb that is in various stages of clinical trials for hematologic malignancies as well as solid tumors." (PMID 34584838, 2021). "In this review, we will provide a comprehensive update on CD47-targeting antibodies for hematological malignancies, including monoclonal and bi-specific antibodies, with a special emphasis on agents in clinical investigation." (PMID 34584838, 2021). "Increasing body of evidence indicates the significance of CD47 in pathogenesis and progression of various hematological malignancies, validating CD47 as a candidate for targeted therapy." (PMID 34584838, 2021). "The ubiquitous high level of CD47 gene expression in many hematological malignancies and its impact on the clinical outcomes and prognosis will be discussed." (PMID 32677994, 2020). "This supported many preclinical and clinical trials that have investigated the safety and the efficacy of anti-CD47 in treating most of the hematological malignancies." (PMID 32677994, 2020). "Among the new potential therapeutic mAbs, CD47 is emerging as a new target in the context of solid tumor and hematological malignancies." (PMID 32899714, 2020).
hematologic malignancies (continued). "We will focus on pre-clinical and clinical studies targeting the CD47 axis in hematological malignancies." (PMID 32677994, 2020). "CD47/SIRPα-based therapies have been proven as an effective treatment for solid tumors and hematologic malignancies, with several clinical trials including CD47-blocking monoclonal antibodies or SIRPα-Fc fusion protein." (PMID 31829270, 2019). "Many solid and hematologic malignancies express CD47 on their cell surface to display an anti-phagocytic signal to SIRPα-expressing myeloid cells and evade destruction by innate and adaptive immune system." (PMID 28077173, 2017). "Hence, blockade of CD47/SIRPα signaling was regarded to increase phagocytosis by TAMs in solid tumors and hematological malignancies." (PMID 40050933, 2025). "CD47 was first reported as a promising target antigen in the context of hematologic malignancies." (PMID 40402266, 2025). "In addition, we discuss the potential and challenges of targeting the CD47-SIRPα axis in the treatment of hematological malignancies." (PMID 38464520, 2024). "Clinical trials have been initiated to investigate the effects of combining Azacitidine (Aza), an anti-metabolite chemotherapy drug, with CD47/SIRPα inhibition, such as the anti-CD47 monoclonal antibody (mAb) Magrolimab, in patients with hematologic malignancies." (PMID 39040441, 2024). "CD47 is strongly expressed in various solid tumors and hematologic malignancies." (PMID 38983860, 2024). "SRF231 is an anti-CD47 fully human IgG4 monoclonal antibody that binds CD47 on the surface of RBCs but does not cause phagocytosis; it has been proposed in Phase 1 preclinical model of both advanced solid and hematologic malignancies." (PMID 36293358, 2022). "Accordingly, CD47-targeted BsAbs may be a promising strategy to overcome limitations with CD47 blockades and further improve therapeutic efficacy for hematological malignancies." (PMID 35978372, 2022). "More CD47/SIRPα-targeted BsAbs for hematological malignancies are on the way." (PMID 35978372, 2022). "In addition, CD47 products with improved safety in the future are expected to be more effective in treating hematological malignancies." (PMID 35978372, 2022). "In conclusion, CD47-targeted mAbs combined with current therapies may be an effective treatment option for hematological malignancies." (PMID 35978372, 2022). "In this review, we will provide an update on the landscape of CD47-targeting antibodies for hematological malignancies, including monoclonal and bi-specific antibodies, with a special emphasis on agents in clinical trials and novel approaches to overcome toxicity." (PMID 34584838, 2021). "In contrast, a multicenter, open-label, first-in-human phase 1 study of TTI-621 was conducted, wherein a recombinant soluble fusion protein composed of the CD47-binding domain of human SIRPα and the Fc region of human IgG1, binds to CD47 in patients with R/R hematologic malignancies." (PMID 35008305, 2021). "No update information about using such vehicles in targeting CD47 in hematological malignancies." (PMID 32677994, 2020). "The following section will address the role of CD47 in hematological malignancies." (PMID 32677994, 2020). "A variety of hematological malignancies demonstrate elevated CD47 expression, suggesting that CD47 may mediate immune escape." (PMID 28234345, 2017). "Clinical trials have confirmed that the potency and efficacy of CD47/SIRPα-based therapy, utilizing CD47-blocking monoclonal antibodies (Abs) or SIRPα-fragment crystallizable (Fc) fusion proteins, is a potent and efficacious approach for treating both solid tumors and hematologic malignancies." (PMID 38398223, 2024). "Although there are difficulties in the development of CD47-based immunotherapy for hematological malignancies, such as poor efficacy and hematological side effects, these issues may be solved by the development of bispecific antibodies and the establishment of new drug delivery systems." (PMID 38464520, 2024).